POSTN (periostin)
Diseases named in the same sentence as POSTN in open-access papers (continued):
Sharing a sentence is not in itself a finding about the gene and the disease.
melanoma (continued). "We found that COL-I and FN maintained or enhanced melanoma cell adhesion, whereas POSTN attenuated adhesion and enhanced the migration of melanoma cells in vitro." (PMID 26083413, 2015). "POSTN was expressed in the region surrounding melanoma cell nests in metastatic lesions of both wounded mice and the patient." (PMID 26083413, 2015). "Our results suggest that POSTN is a key factor in promoting melanoma cell metastasis to wound sites by providing a premetastatic niche." (PMID 26083413, 2015). "Together, these findings indicated that POSTN attenuates cell adhesion and promotes the migration of melanoma cells." (PMID 26083413, 2015). "Immunofluorescence analysis of the metastatic lesion revealed that FN was expressed in both stromal and melanoma (Melan-A–positive) cells, whereas POSTN and COL-I were localized only in stromal cells." (PMID 26083413, 2015). "Our findings shed light on the premetastatic niche for melanoma and suggest that targeting of POSTN warrants further investigation as a potential strategy for preventing metastasis." (PMID 26083413, 2015). "In cell lines, expression of COL6A3 stromal cell marker was reduced to less than 1% of the value measured in matched tumors whereas periostin was expressed (at either low or high level) in about half of the melanoma cell lines." (PMID 18086302, 2007). "We next focused on cutaneous melanoma to quantify periostin transcripts in a total of 113 tumor samples, including primary and metastatic lesions, and we correlated periostin expression with Breslow thickness of melanoma primary tumors." (PMID 18086302, 2007). "The increased expression of periostin in melanoma metastatic lesions that we identified in this study is in agreement with in vivo studies revealing that periostin overexpression promotes metastatic growth of cancer cells." (PMID 18086302, 2007). "In melanoma, our study identifies both stromal and melanoma cells as sources of periostin production and correlates POSTN expression levels with increased primary tumor thickness and metastatic process development." (PMID 18086302, 2007). "Identification of the cellular source of periostin production in melanoma metastases -cancer cells or stroma- was assessed by comparing periostin expression in 23 newly-established melanoma cell lines and matched tumors." (PMID 18086302, 2007). "All together, these data suggest that, in about half of the melanoma samples tested, POSTN expression is restricted to stromal cells while, in the other half, cancer cells are another source of periostinproduction." (PMID 18086302, 2007). "Conversely, tumor-invaded lymph nodes with low POSTN expression account for the low levels (<100) measured in a subset of melanoma metastases." (PMID 18086302, 2007). "Classification of melanoma metastases showed that very low POSTN expression levels are found in metastases located in organs with low endogenous periostin expression, like the liver or lymph nodes." (PMID 18086302, 2007). "Although periostin expression levels were variable in melanoma tumors, average POSTN expression level was significantly higher in metastases compared to primary lesions (P = 0.03)." (PMID 18086302, 2007). "Here, we relied on a revised version of Breslow classification based on primary tumor thickness to correlate periostin expression with prognosis of melanoma." (PMID 18086302, 2007). "Periostin overexpression in (sub)cutaneous melanoma metastases is more difficult to assess as POSTN transcripts are already abundant in normal skin." (PMID 18086302, 2007). "In contrast to the reduction by more than 99% of COL6A3 stromal marker mRNA in all cell lines, significant POSTN transcription was maintained in some melanoma cell lines, suggesting that both stromal cells and melanoma cells express periostin." (PMID 18086302, 2007). "Periostin expression in melanoma was compared to the expression level in nine normal skin or benign nevus tissues." (PMID 18086302, 2007).
melanoma (continued). "On the other hand, our data indicate that stromal cells are an important source of periostin production in melanoma tumors." (PMID 18086302, 2007). "Conversely, periostin levels should be high if melanoma metastases overexpress POSTN either through acquisition of POSTN expression by melanoma cells or to increased periostin expression in tumor-associated stromal cells." (PMID 18086302, 2007). "In that respect, about 60% of melanoma metastatic tumors in the liver or lymph nodes showed a clear POSTN overexpression compared to normal organs." (PMID 18086302, 2007). "In our study, we show a strong correlation between high expression of POSTN in melanoma cells and resistance formation, where the source of POSTN could be malignant cells and stromal cells, such as CAFs." (PMID 38942020, 2024). "In our co-culture experiments, melanoma cells were efficiently killed by MEKi treatment despite the presence of macrophages, unless the latter where pre-exposed to POSTN, indicating that POSTN-polarized TTR macrophages mediate resistance formation against targeted therapy in melanoma." (PMID 38942020, 2024). "Some studies indicate that periostin (a contributing factor in tumorigenesis) and M2 macrophages may play a crucial role in melanoma progression through inflammation." (PMID 36676131, 2023). "In another report, immunohistochemical analysis showed that POSTN was expressed in invasive and metastatic human melanoma, which could accelerate melanoma progression in a mouse melanoma model." (PMID 35409404, 2022). "In aggregate, POSTN could promote tumor growth by stimulation of TAMs to induce angiogenetic factors in melanoma." (PMID 35409404, 2022). "Indeed, periostin, collagen type I, and fibronectin were shown to be upregulated in a metastatic lesion that developed at a wound site in a patient with melanoma." (PMID 34200480, 2021). "The extracellular matrix protein periostin (POSTN) is expressed in the region surrounding melanoma cell nests in metastatic melanoma lesions, and could be a stimulator for TAMs in melanoma." (PMID 32707850, 2020). "Furthermore, we confirmed that periostin promotes the proliferation of murine and human melanoma cells in vitro." (PMID 30621220, 2019). "Our findings indicate that periostin and M2 macrophages play a critical role in melanoma progression and prognosis in both humans and mice, indicating that periostin is a potential target for treating progressive melanoma." (PMID 30621220, 2019). "Notably, the stromal expression of periostin was significantly enhanced in the melanomas developed in inflamed mice compared with those in the control mice." (PMID 30621220, 2019). "Targeting the interaction of periostin with other proteins may be a promising strategy for developing new therapies for melanoma." (PMID 30621220, 2019). "To verify the effect of periostin on the proliferation of melanoma cells, we next examined whether periostin could promote the cell growth of B16F10 murine melanoma cells and A375 human melanoma cells in vitro." (PMID 30621220, 2019). "The expression levels of periostin in melanoma are relatively high compared with those in other malignancies, which may be related to the fact that the skin is a site where periostin is highly expressed." (PMID 30621220, 2019). "In our study of human melanoma, periostin was highly expressed in the stroma of thick melanomas." (PMID 30621220, 2019). "Consequently, melanoma development and progression is associated with an increase in fibrillar network of ECM proteins (like collagen I, fibronectin, and periostin) around the melanoma cells." (PMID 30701028, 2018). "In addition, TAMs are prominent in the tumor stroma in melanoma, and POSTN stimulates CD163+ macrophages to produce several specific cytokines including Treg-related chemokines [chemokine ligand 17 (CCL17), CCL22]." (PMID 29410946, 2018).
melanoma (continued). "Notably, immunofluorescence staining revealed that CD163+ macrophages were distributed in POSTN-expressing areas, suggesting that POSTN in melanoma can stimulate CD163+ macrophages to produce CXCL5." (PMID 29643991, 2018). "In the same study, other genes such as COL5A1, periostin (POSTN), thrombospodin 2 (THBS2) and LOX were upregulated and associated with poor survival after adjuvant chemotherapy; these genes were also upregulated in our melanoma case series." (PMID 28743863, 2017). "Moreover, the addition of TGFβ-neutralising antibody to cultures of fibroblasts in melanoma-cell-conditioned media prevents the upregulation of periostin." (PMID 27515461, 2016). "Another group found that periostin was overexpressed in a clinical case of melanoma metastasis and subsequently showed that inhibition of this protein in stromal cells leads to enhanced adhesion and reduced metastatic spread in a murine melanoma model." (PMID 27358011, 2016). "Indeed, downregulation of POSTN reduced the incidence and extent of metastasis in vivo, implicating POSTN as a major niche component for metastasis of melanoma to wound sites." (PMID 26083413, 2015). "On the basis of this clinical experience, we examined which ECM proteins produced during wound healing may contribute to the induction of wound metastasis in melanoma and identified POSTN as a key factor attracting melanoma cells to injured sites." (PMID 26083413, 2015). "Furthermore, βig-H3 observed at the invasion front of melanomas co-localized with fibrillar fibronectin/tenascin-C/periostin structures, suggesting an important role for βig-H3 in ECM deposition and invasive growth of melanoma cells." (PMID 22949874, 2012). "Hence, these data demonstrate the POSTN overexpression in about 60% of melanoma metastases in the liver or lymph nodes." (PMID 18086302, 2007). "Therefore, our data suggest that, in metastatic melanoma tumors, periostin expression can be induced in melanoma cells." (PMID 18086302, 2007). "We measured the level of POSTN transcripts in 23 melanoma cell lines and matched tumors." (PMID 18086302, 2007). "Notably, very low expression levels (<10) were measured in 9% of melanoma metastases while 15% of them showed very high levels of POSTN expression (>2000)." (PMID 18086302, 2007). "Finally, to compare the periostin expression levels in other cancer cell lines with the values obtained in melanoma, we selected a series of 19 cell lines derived from tumors of various cancer types." (PMID 18086302, 2007). "Melanoma metastases were characterized by highly variable POSTN expression levels." (PMID 18086302, 2007). "To test whether POSTN or MDK could directly affect the responsiveness of melanoma cells to MAPK inhibitors, we first identified primary melanoma cell lines displaying either high or low endogenous POSTN and MDK expression (M150325, M131205 and M150543, M161201, respectively)." (PMID 38942020, 2024). "Thus, neither POSTN nor MDK altered the susceptibility of melanoma cells to MEKi-induced cell death." (PMID 38942020, 2024). "Also, it was shown that the main sources of periostin are melanoma and stromal cells." (PMID 36224629, 2022). "Finally, in a murine model of melanoma within an inflammatory environment as well as in the skin of melanoma patients the recruitment of M2 macrophages was promoted in the presence of high periostin levels." (PMID 33466303, 2021). "Therefore, we immunohistologically examined the expression of stromal periostin and the infiltration of CD163+ M2 macrophages in 94 melanoma samples, and statistically analyzed the associations of these variables with the patients’ histological features, clinical stage, and prognosis." (PMID 30621220, 2019). "Finally, we attempted to confirm a role for POSTN in the colonization of melanoma cells in vivo." (PMID 26083413, 2015). "Hence, these results indicated that POSTN promotes metastasis of melanoma." (PMID 26083413, 2015).
melanoma (continued). "In vivo, two reports demonstrated that POSTN overexpression in tumor cell lines increases metastasis and angiogenesis in nude mice and reduces stress-induced apoptosis while another report provided evidence that periostin suppresses lung metastasis of mouse melanoma cell line B16-F10." (PMID 18086302, 2007). "The induction of periostin expression in melanoma cells may be a consequence of mutagenic events occuring during the tumorigenic processes or may be the result of interactions with stromal components previously reported to influence development and progression of carcinomas." (PMID 18086302, 2007). "On the other hand, periostin expression in melanoma cells is probably acquired during the tumorigenic process as 1) normal melanocytes do not express POSTN and 2) melanoma cells from distinct metastases of the same patient were associated with very different levels of periostin expression." (PMID 18086302, 2007). "Hence, this work suggests that, in melanoma, periostin overexpression may also be involved in the process of metastasis." (PMID 18086302, 2007). "Other ARGs, including OLR1, KCNJ8, APP, POSTN, and STC1 showed significant yet heterogenous relationships with immune cells subsets, reinforcing the complexity of immune regulation in melanoma." (PMID 40943183, 2025). "For example, POSTN from CAFs stimulates TAMs to produce CXCL5 to enhance PD-L1 expression in TAMs, maintaining regulatory T cells in melanoma." (PMID 35409404, 2022). "This led us to investigate if periostin and CD163+ M2 macrophage infiltration were prognostic factors in human melanoma." (PMID 30621220, 2019). "The stromal expression of periostin was upregulated in inflamed skin, and significantly more CD163+ M2 macrophages were recruited to the melanomas in inflamed skin." (PMID 30621220, 2019). "Recently it was reported that POSTN accelerates proliferation of several types of cancer cells, such as gastric cancer and melanoma cells, while we found that B16-BL6 and MeWo cells manifested similar growth rates in the absence or presence of POSTN." (PMID 26083413, 2015). "We now show that POSTN, COL-I, and FN components of fibrillar networks were upregulated in a metastatic lesion that developed at a wound site in a patient with melanoma." (PMID 26083413, 2015). "Together, these observations suggested that POSTN, COL-I, and FN components of fibrillar networks were overexpressed in the dermal matrix surrounding melanoma cell nests as well as in perivascular regions of the metastatic lesion." (PMID 26083413, 2015). "To evaluate the effects of POSTN in the metastatic tumor microenvironment, we studied B16-BL6 and the human melanoma cell line MeWo, both of which contain only small amounts of Postn and POSTN mRNA, respectively." (PMID 26083413, 2015). "By comparing gene expression in the primary and wound metastatic lesion of the melanoma patient, we found that among genes related to wound healing, genes of ECM proteins, including POSTN, COL1A1, and FN1, were overexpressed in the wound metastatic lesion." (PMID 26083413, 2015). "To gain more insight into the nature of periostin-producing cells in metastatic lesions, we measured POSTN expression levels in newly established melanoma cell lines and matched tumors." (PMID 18086302, 2007). "In our study, however, treatment with recombinant POSTN neither resulted in stabilization of the MAPK pathway nor increased survival of melanoma cells upon MEKi treatment, suggesting that POSTN plays an indirect effect on resistance formation." (PMID 38942020, 2024). "As POSTN and MDK were unable to directly drive resistance in melanoma cells, we examined the cell populations that could be affected by POSTN or MDK." (PMID 38942020, 2024). "Around 60% of melanoma metastatic tumors in the liver or lymph nodes overexpress periostin, although periostin expression is not increased in primary tumors." (PMID 36224629, 2022).
melanoma (continued). "Kaplan-Meier analysis revealed that patients with high expression of periostin had significantly shorter disease-free survival (DFS) and melanoma-specific survival (MSS) (DFS: hazard ratio (HR) 2.832, 95% confidence interval (CI) 1.267–6.329, p = 0.011; MSS: HR 2.980, 95% CI 1.148–7.741, p = 0.013)." (PMID 30621220, 2019). "However, no studies have comprehensively investigated the relationships between periostin and CD163+ M2 macrophages regarding the progression and prognosis in patients with melanoma." (PMID 30621220, 2019). "Infiltrating secondary carcinomas and melanomas that had metastasised to bone showed a similar pattern of staining for periostin in surrounding non-neoplastic bone." (PMID 30202513, 2018). "Intricate fibrillar networks composed of POSTN, COL-I, and FN are also assembled in lymph node macrometastases of melanoma, whereas such networks are rarely observed in lymph node micrometastases, suggesting that the network formation is associated with the aggressiveness of metastasis." (PMID 26083413, 2015). "POSTN attenuated the cell adhesion and promoted the migration of melanoma cells without affecting their proliferation in vitro." (PMID 26083413, 2015). "Given that normal melanocytes do not express periostin, this study suggests that melanoma cells sometimes acquire the ability to express the gene during tumorigenesis." (PMID 18086302, 2007). "In these organs, low POSTN expression levels are expected if melanoma cells do not produce periostin." (PMID 18086302, 2007). "In melanoma samples, average periostin expression is not increased in primary tumors whereas POSTN overexpression was detected in about 60% of melanoma metastatic tumors in the liver or lymph nodes." (PMID 18086302, 2007). "Data also suggest that high level of periostin expression in metastatic tumoral cells is not time-dependent as variable expression levels were observed during the tumor resection history of melanoma patients LB2174 and LB2077." (PMID 18086302, 2007). "In melanoma, POSTN transcription was not increased in primary lesions compared to normal skin but was correlated with Breslow thickness." (PMID 18086302, 2007). "Not only melanoma, but non-melanoma skin cancers also express POSTN in cancer stroma." (PMID 35409404, 2022). "Thus, higher concentrations of full-length POSTN appear to predominantly affect adhesion and migration rather than proliferation of melanoma cells." (PMID 26083413, 2015). "These variations may be explained by distinct localization of melanoma metastases as normal skin produces significant amounts of periostin unlike other organs with very low endogenous levels of periostin, like lymph nodes or the liver." (PMID 18086302, 2007). "To address whether POSTN expression leads to presence of intratumoral TTR macrophages and resistance formation to targeted therapy in vivo, we sought to establish an immunocompetent melanoma mouse model system that is normally responsive to inhibition of the MAPK kinase pathway." (PMID 38942020, 2024). "Since serum sCD163 and CXCL5 are, at least in part, derived from CD163+ TAMs that are activated by periostin, and chemokine profiles from TAMs are determined by the stimulation of stromal factors, spontaneously produced TAM-related factors could be detected in serum from melanoma patients." (PMID 31080803, 2019). "Hence, these data suggest that expression of periostin by cancer cells is not restricted to melanoma cells but may also occur in other cancer types." (PMID 18086302, 2007). "Investigation of 46 primary cutaneous melanoma lesions did not reveal any significant difference in average POSTN expression compared to normal tissues although we found that, in primary melanoma, thicker tumors (> 4 mm) may be correlated with increased periostin expression (P = 0.07)." (PMID 18086302, 2007).